GPX4 (glutathione peroxidase 4)
Diseases named in the same sentence as GPX4 in open-access papers (continued):
Sharing a sentence is not in itself a finding about the gene and the disease.
cancer (continued). "Further, Gpx deficiency leads to cancer predisposition and in vivo sensitivity to oxidant-inducing agents is well documented for mice lacking selenocysteine-containing proteins such as Gpx1 and Gpx4." (PMID 26147969, 2015). "At the molecular level, significant upregulation of GPX4 and GSTA2 was observed in both cancer cell lines, whereas NFKB expression increased selectively in HT-29 cells, with no notable changes in CAT or SOD1 expression." (PMID 41745011, 2026). "During EMT, cancer cells become more flexible due to increased PUFA content, which in turn heightens their dependence on GPX4." (PMID 41596341, 2026). "Molecular analyses confirmed reduced hTERT and GPX4 expression, along with GSH depletion, ROS accumulation, and elevated lipid peroxidation-collectively promoting enhanced cancer cell death." (PMID 41682351, 2026). "In this review, we will focus on the design and synthetic strategies that led the advancements of PROTACs as a cancer therapy for the targeted degradation of poly ADP-ribose polymerases (PARPs), glutathione peroxidase 4 (GPX4) and epigenetic regulators." (PMID 41885448, 2026). "Recent studies have demonstrated that the use of GPX4 inhibitors such as RSL3, ML210, ML162, and FIN56 can effectively induce ferroptosis in cancer cells." (PMID 40136465, 2025). "First, although we characterized the role of the PAX8‐AS1/GPX4 axis in ICC, its generalizability to other cancer types remains unexplored." (PMID 40391780, 2025). "Ferroptosis is regulated by various genes, including the ferroptosis‐suppressor genes (GPX4, SLC7A11, and FTH1), which have been identified as potential targets for cancer therapy." (PMID 39297393, 2025). "Anti-ferroptotic functions include MFN1-mediated mitochondrial fusion, which reduces ferroptosis sensitivity in cancer cells, as well as the activation of stress response pathways via DELE1 and ATF4, which enhance GSH synthesis and GPX4 stability." (PMID 40919170, 2025). "Accumulating evidence has shown that METTL3 regulates ferroptosis in various cancers by modulating key factors such as SLC7A11, GPX4 and FSP1." (PMID 40175350, 2025). "Moreover, 3′- UTR has been revealed to be effective RNA-based therapy tools for treating cardiac diseases irrespective of its cognate protein, the findings in this study suggested that mutated SLC7A11, GPX4 and CP 3′-UTRs may be effective RNA-based therapeutic targets for DOXIC in cancer patients." (PMID 40915108, 2025). "First, Pan-cancer transcriptomic analysis of The Cancer Genome Atlas revealed a positive correlation between IL4I1 and GPX4, a key ferroptosis suppressor." (PMID 41354345, 2025). "We also show that dual inhibition of GPX4 and GPX1 synergistically inhibits cancer cell growth, validating the effectiveness of targeting this compensatory metabolic mechanism." (PMID 40259435, 2025). "Several key proteins interacting with ATF4 such as NRF2, GPX4, SLC7A11, PDIA4 have been suggested as mediators of the role ATF4 plays in preventing ferroptosis in various cancer models." (PMID 40667288, 2025). "In previous studies, cancer treatment targeting ferroptosis has mainly been limited to solute carrier family 7a member 11 (SLC7A11) and GPX4, and currently, therapies targeting ferritinophagy receive increasing attention." (PMID 39844412, 2025). "Conversely, OE19-PS cells were exquisitely sensitive to GPX4 inhibition by RSL3, consistent with the specific vulnerability of persistent cancer cells to ferroptotic inducers." (PMID 40473905, 2025). "This process blocks lipid peroxidation independently of GPX4 and is mainly active in KEAP1-mutant cancers, where FSP1 expression is elevated due to NRF2 activity." (PMID 40733290, 2025). "The autophagic degradation of N-cadherin has recently been identified in cancer cell lines as a mechanism of ferroptosis, mediated by the selective cargo protein hippocalcin-like 1 (HPCAL1) and operating independently of GPX4 regulation or iron metabolism." (PMID 41304754, 2025).
cancer (continued). "To enhance Tempol’s efficacy, we investigated its interaction with ML210, a GPX4 inhibitor, in human colon (HT29) and gastric (CRL-1739) cancer cell lines." (PMID 41150804, 2025). "Using protein covariation network analysis, this study uncovers the mechanism of action for AX-53802, a new ferroptosis inducer, validating GPX4 as its direct target, and proposes combination therapies targeting FAK/Src to enhance cancer cell death." (PMID 40164758, 2025). "An acid and GSH dual-controlled nanoplatform enhances cancer treatment by using triptolide to regulate NRF2 and inhibit GSH protein expression, reducing GPX4 activity and promoting ferroptosis, while minimizing toxicity." (PMID 40490812, 2025). "Inhibitors of GPX4, such as ML210, effectively induce ferroptosis in diverse cancer models, including drug-resistant settings both in vitro and in vivo." (PMID 41150804, 2025). "Glutathione Peroxidase 4 (GPX4) is a critical lipid peroxidase that prevents ferroptosis, and its inhibition has emerged as a strategy to sensitize cancer cells to oxidative stress." (PMID 41150804, 2025). "In certain cancers, including BRCA, THCA, and UCEC, GPX4 appears to be protective, whereas in others like COAD, LAML, and UVM, it acts as a risk factor." (PMID 41142608, 2025). "Among the various mechanisms governing ferroptosis sensitivity in cancer cells, the solute carrier family 7 member 11 (SLC7A11)—reduced glutathione (GSH)—GPX4 axis plays a fundamental role." (PMID 40569831, 2025). "Cancer cells scavenge lipid hydroperoxides using glutathione (GSH) and glutathione peroxidase 4 (GPX4)." (PMID 40229247, 2025). "Cancer cells were typically isolated and selected for a strong xCT/GSH/GPX4 axis and robust GSH synthesis that buffers ROS accumulation." (PMID 40694424, 2025). "In our study, the Nrf2/HO-1/GPX4 pathway emerged as a key pathway for LDR plus ICI to induce ferroptosis, consequently leading to cancer cell death." (PMID 40539046, 2025). "As a cofactor of GPX4, GSH is essential for protecting cells from various oxidative stress injuries; however, cancer cells utilize this mechanism to avoid ferroptosis." (PMID 40242036, 2025). "Here we demonstrate that macrophages co-cultured with ferroptotic cancer cells from various types effectively mitigate cell death induced by GPX4 inhibitors (RSL3 and ML162), GPX4 silencing via shRNA, or the Xc- system inhibitor IKE." (PMID 41326365, 2025). "By binding to GPX4 promoters,β-catenin and TCF4 transcription factor complexes can promote GPX4 expression, inhibiting ferroptosis and making cancer cells resistant to drugs." (PMID 40969276, 2025). "It stabilizes pro-tumorigenic KYNU protein, promotes cancer stemness via WNT/β-catenin signaling, inhibits ferroptosis through the miR-335-5p/GPX4 axis, and modulates innate immunity via DHX9 interaction." (PMID 40852728, 2025). "Recent reports have shown that ectopic expression of NSUN2 drives ferroptotic resistance in cancer cells through modulating a list of target genes, such as SLC7A11, NRF2 and GPX4." (PMID 39742570, 2025). "In this study, we apply novel multiplex immunoassays to interrogate biomarkers of ferroptosis and pyroptosis and provide evidence that a commonly used ferroptosis inducer, the GPx4 inhibitor RSL3, also induces pyroptosis in cancer cells." (PMID 40652037, 2025). "Lip-1 is reported to inhibit ferroptosis through inactivation of lysosomal iron triggering ferroptosis in cancer cells, while (1S, 3R)-RSL3 enhances intracellular accumulation of lipid hydroperoxides by inhibiting GPX4." (PMID 41291487, 2025). "Currently, GPX4 inhibitory means (BBP-954, DC-2, and DMOCPTL) have been recognized as possible therapeutic approaches for addressing cancer progression and metastasis, and relevant preclinical experiments are underway 31-33." (PMID 40860189, 2025). "Regulated NRF2/HMOX1/GPX4 axis and decreasing GSH as a GSH oxidase, which sensitized cancer cells to radiotherapy and immunotherapy." (PMID 40200790, 2025).
cancer (continued). "Several preclinical studies have demonstrated the efficacy of direct GPX4 inhibitors such as RAS-selective lethal 3 (RSL3) and molecular libraries 162 (ML162) in inducing ferroptosis across a range of cancer models, including HNSCC." (PMID 40650229, 2025). "Subsequent analysis also demonstrated a clear relationship between GPX4 expression and key immune checkpoints such as VEGFB, TGFB1, CD276, TNFRSF18, and TNFRSF4 across most cancer types." (PMID 41142608, 2025). "One metabolite in the cholesterol biosynthetic pathway, isopentenyl pyrophosphate (IPP), regulates the activity of glutathione peroxidase 4 (GPX4), which inhibits ferroptosis to promote cancer cell survival." (PMID 40422882, 2025). "Upon H2O2 stimulation, GPX4 expression increased whilst GPX1 decreased, suggesting complementary roles for GPX4 and GPX1 in cancer cells." (PMID 40259435, 2025). "Together, our in vitro, in silico, and in vivo data indicate that LDHB and GPX4 work in parallel to suppress lipid peroxidation, particularly in mitochondria, thereby corroborating our hypothesis that LDHB is an important contributor to suppress mitochondria-associated ferroptosis in cancer cells." (PMID 40090955, 2025). "Aberrant activation of glutathione peroxidase 4 (GPX4), a key antioxidant enzyme, confers resistance to radiation and chemotherapy-induced iron death to cancer cells." (PMID 38952556, 2024). "It has been reported that the ferroptosis regulatory system (GPX4) and anti-oxidative enzymes (GPX1) contribute to anti-cancer drug resistance." (PMID 38182643, 2024). "Collectively, targeting ferroptosis by inhibiting GPX4 in intratumoral Tregs seems to be a promising strategy for reprogramming the TME and treating cancer." (PMID 38453898, 2024). "Specifically, targeting key antioxidant proteins, such as SLC7A11, GCLC, GPX4, TXN, and TXNRD, represents an emerging approach for inducing oxidative cell death in cancer cells." (PMID 39090114, 2024). "Our findings demonstrate that GPx4 inhibitors, such as RSL3 and ML210, indirectly and directly induce ferroptosis in cancer cells cocultured with macrophages." (PMID 38429255, 2024). "Cancer cells treated with cisplatin show decreases in GSH and inactivation of GPX4, initiating ferroptosis." (PMID 39201357, 2024). "In summary, our results revealed a regulatory mechanism by which HMGA2 coordinates GPX4 expression and underscores the potential value of targeting HMGA2 in cancer treatment." (PMID 38493165, 2024). "Adipose-derived exosomes can promote chemoresistance to oxaliplatin via transpotting exosomal microsomal triglyceride transfer protein (MTTP) into cancer cells and thus regulating PRAP1/ZNFE1/GPX4 signal pathway." (PMID 38737906, 2024). "Techniques such as CRISPR-Cas9 and RNAi can be employed to knock out ferroptosis-inhibiting genes like GPX4 or enhance the expression of ferroptosis-promoting genes, such as ACSL4 and SAT1, which facilitate lipid peroxidation in cancer cells." (PMID 39871848, 2024). "Additionally, although GPX4 loss-induced ferroptosis may not directly inhibit cancer cell tumorigenesis, ferroptosis can induce immunosuppression by promoting MDSC recruitment." (PMID 39614322, 2024). "GSH depletion can trigger ferroptosis, which has been exploited in cancer treatments, and supplementation with GSH is utilized by glutathione peroxidase 4 (GPX4) to prevent lipid peroxidation, in turn inhibiting ferroptosis." (PMID 38287398, 2024). "Both GPX4 and TXNRD1 are reported to contribute to cancer proliferation and resistance to ferroptosis." (PMID 38182643, 2024). "Since SLC7A11 is the upstream regulator of GPX4, we further elucidate the role of SLC7A11 in the anti-cancer effect of SFN against OS." (PMID 39657365, 2024). "For instance, miRNAs regulate GPX4 expression, an enzyme crucial in the GSH-GPX4 pathway, across diverse diseases, including cancer and NDs." (PMID 39036600, 2024).
cancer (continued). "In the following sections, we will introduce several common categories of ferroptosis inducers utilized in cancer treatment, including SLC7A11 and GPX4 inhibitors, as well as the repurposing of clinical drugs as ferroptosis inducers." (PMID 39624080, 2024). "FSP1 expression strongly correlates with the resistance of cancer cell lines to ferroptosis induced by GPX4 inhibitors and FSP1 expression is amplified in some cancers." (PMID 38908072, 2024). "For instance, cisplatin-resistant cancer cells overexpress the Wnt pathway membrane receptor, frizzled homolog 7 (FZD7), leading to activation of TP63 and subsequently enhanced GPX4 expression." (PMID 39015566, 2024). "In our study, the combination NRF2 inhibitors can further suppress cell viability and induce cell death when compared to the single use of GPX4 inhibitors in HM and OVCA429 cancer cell lines." (PMID 38396022, 2024). "Inhibiting GPx4 expression, RSL3 is also known as a ferroptosis inducer, which has been demonstrated in several cancer types." (PMID 38539894, 2024). "Given the crucial role of GSH in regulating redox balance, certain molecules involved in GSH metabolism, such as GPX4 and SLC7A11, have been identified to impede ferroptosis in cancer cells." (PMID 39548421, 2024). "The present study demonstrated that the ferroptosis induced by the GPx4 inhibitors RSL3 and ML210 increased when the cancer cells were co-incubated with macrophages." (PMID 38429255, 2024). "Curcumin promotes the antiproliferation and ferroptosis of the colon and lung cancer cells by downregulating ferroptosis-inhibiting genes (SLC7A11 and GPX4)." (PMID 38892270, 2024). "The antioxidant pathway in ferroptosis is intricately linked to the activation of key components such as system Xc−, GPX4, and NRF2, particularly in the context of cancer." (PMID 39104501, 2024). "Studies on cancer cells with high CAV1 expression have shown that the expression of NOX1 and ACSL4 is increased, and the expression of FTH1 and GPX4 is decreased, which reduces sensitivity to ferroptosis." (PMID 38313306, 2024). "The key factor involved in the process, as demonstrated for other cancer cell lines, was found to be Ras-Sensitive Ligand 3 (RSL3), an inhibitor of the glutathione peroxidase 4 gene (GPX4)." (PMID 39595047, 2024). "In conclusion, the specific ablation of TAU, Shank3, and GPX4, along with utilizing MWA technology, presents new opportunities for studying ND and cancer induced by ferroptosis." (PMID 38962561, 2024). "Genes such as PARP1, NAMPT, AIMP2, MCL1, and TOMM20 exhibited widespread amplifications of CNVs in multiple cancers, while genes like RNF146, GPX4, ESR1, CUL4A, and PTEN showed widespread deletions." (PMID 38499384, 2024). "Enzymes such as glutathione peroxidase 4 (GPX4) play a crucial role in regulating ferroptosis, and it has emerged as a potential target for cancer therapy." (PMID 39104501, 2024). "The levels of GPX4, SLC7A11, and SLC3A2 were reduced in cancer cells treated with either BRD4 knockout or JQ-1." (PMID 38565708, 2024). "Treatment with DSF/Cu led to increased lipid peroxidation, upregulation of HMOX1, and decreased levels of GPX4 and GSH, ultimately inducing cancer cell death through ferroptosis." (PMID 39867656, 2024). "BEBT-908, which is a dual PI3K/HDAC inhibitor, triggers a robust ferroptotic response in cancer cells, characterized by the reduction of SLC7A11 and GPX4, heightened lipid ROS and MDA levels, and activation of ferroptotic signaling." (PMID 38562143, 2024). "The authors proved that G3P supplementation can inhibit RSL3-induced ferroptosis in different cancer cell lines and that GPD2 deletion significantly sensitized cells to GPX4 inhibitors, and this was accompanied by increased mitochondrial lipid peroxidation." (PMID 38539832, 2024).
cancer (continued). "Notably, we further explored whether RPLP2 upregulation was linked to ferroptosis in seven other cancers where RPLP2 was most significantly upregulated, and the results indicated that RPLP2 also showed significant correlation with GPX4 in five cancer types including GBM, LGG, PAAD, TGCT and THYM." (PMID 37980521, 2023). "Taken together, the high expression pattern of GPX4 was TME-specific, and emphasized the clinical utility of GPX4 as a predictive biomarker in cancer immunotherapy." (PMID 38065948, 2023). "Statins can prevent the biosynthesis of GPX4 by blocking the MVA pathway, which inhibits cancer cells." (PMID 37833746, 2023). "Future studies will be required to explore the potential and safety of drug candidates that simultaneously target GPX4 and the NRF2/HO‐1 axis in cancer patients." (PMID 36658724, 2023). "Furthermore, histone H3 lysine-4 trimethylation and acetylation of histone H3 on lysine 27 have been demonstrated to be enriched at the upstream site of GPX4 in different types of cancer tissues, indicating that the high expression of GPX4 may be the result of methylation." (PMID 37488128, 2023). "Triggers ROS storm, GSH depletion, GPX4 inactivation, and LOX catalysis, promote ferroptosis in cancer cells and enhance IFNγ and AA action." (PMID 38288118, 2023). "Novel nitroisoxazole‐containing spiro[pyrrolidine‐oxindoles] were designed as dual inhibitors of GPX4 and mouse double minute 2 (MDM2) to induce both ferroptosis and apoptosis in cancer cells." (PMID 36658724, 2023). "Additionally, GPX1, GPX2, and GPX4 expression is upregulated in cancer cells resistant to many chemotherapeutics, and many treatment-resistant cells have been found to accumulate lipid peroxides, showing an increased dependence on the antioxidant activity of GPX4." (PMID 37244126, 2023). "GPX4 is a potential target that can reshape the TME; its use is thus beneficial in cancer therapy and points to a direction future research can take." (PMID 37325669, 2023). "By contrast, Fer-1 rescued the alterations in markers of ferroptosis (GPX4 and SLC7A11) and cancer cell stemness (Oct4 and Sox2) induced by JYQHD." (PMID 37700383, 2023). "A central regulator of ferroptosis is glutathione peroxidase 4 (GPX4), which protects cells by eliminating lipid peroxides, and cancer cells with mesenchymal or metastatic property are highly susceptible to ferroptosis." (PMID 37180489, 2023). "In U-2 OS osteosarcoma cells treated with GPX4 inhibitor 1S, 3R-RSL3 (hereafter RSL3), a CRISPR/Cas9 screening was conducted using apoptosis and a cancer single-stranded RNA (sgRNA) subpool to identify FSP1 as a potent ferroptosis defense factor." (PMID 37762411, 2023). "xCT controls redox homeostasis and ferroptosis in cancer by inducing the synthesis of GSH and the activation of GPX4." (PMID 37718459, 2023). "Among 610 cancer cell lines, those with high ZEB-1 transcription levels were remarkably more sensitive to a GPX4 inhibitor." (PMID 37046995, 2023). "Accumulating evidence has demonstrated that glutathione peroxidase 4 (GPX4) is a key regulator of ferroptosis, an essential regulator of ferroptotic cancer cell death, and an inflammatory mediator." (PMID 36718277, 2023). "However, the process that affects ferroptosis by regulating GPX4 in cancer remains unclear." (PMID 37248295, 2023). "Cryptotanshinone was found to induce ferroptosis in various cancer cell types by inhibiting the levels of SCL7A11, GPX4, and FPN and increasing the accumulation of ROS." (PMID 37833746, 2023).